USP7 (ubiquitin specific peptidase 7)
Diseases named in the same sentence as USP7 in open-access papers (continued):
Sharing a sentence is not in itself a finding about the gene and the disease.
breast carcinoma (continued). "The authors proved that LINC02582 stabilizes CHK1 via USP7 and demonstrated the significance of the miR-200c/LINC02582/USP7/CHK1 axis in radioresistance of breast cancer cells." (PMID 32585857, 2020). "USP7 promotes radioresistance of breast cancer cells by controlling CHK1 protein stability via direct deubiquitination." (PMID 31601781, 2019). "The miR-200c/LINC02582/USP7/CHK1 signaling axis plays important role in regulating the radiosensitivity of breast cancer cells." (PMID 31601781, 2019). "Our results suggested that the miR-200c/LINC02582/USP7/CHK1 signaling axis is a potential target to improve the response of breast cancer to radiation therapy." (PMID 31601781, 2019). "We tested the expression and intercellular localization of USP7 protein by immunohistochemical staining in tissue sections of primary breast cancer." (PMID 31730000, 2019). "The expression of USP7 is very high in breast cancer sections with low MP scores, while USP7 levels are low in MP high breast cancer sections." (PMID 31730000, 2019). "It remains unclear whether USP7 also has a radiosensitizing effect in breast cancer tumors, for which a defect in HR has frequently been observed." (PMID 38672118, 2024). "Furthermore, a high expression of USP7 also correlated with the presence of lymph node metastases, which is in line with our observations in breast cancer in the in silico analysis." (PMID 38672118, 2024). "Overall, the results show that USP7 inhibition results in a significant radiosensitization of proliferating cells due to an efficient disruption of HR repair and amplification of irradiation-induced replication stress in breast cancer cell lines." (PMID 38672118, 2024). "The heterogeneous mRNA expression level of USP7 in the molecular breast cancer subtypes confirmed our choice to use cell lines with an expression level of USP7 close to the normal tissue of different molecular subtypes and to deregulate the USP7 expression artificially." (PMID 38672118, 2024). "Next, it was investigated whether USP7 is differentially expressed in the different breast cancer subtypes." (PMID 38672118, 2024). "Interestingly, the levels of DICER protein were significantly negatively correlated with those of USP7 in different breast cancer cells." (PMID 37867415, 2024). "USP7 has also been shown to stabilize geminin in breast cancer cells." (PMID 38672118, 2024). "By generating autochthonous breast cancer mouse models, we could show that overexpression of C16orf72/HAPSTR1 or USP7 independently accelerates Pik3caH1047R-driven mammary tumor formation." (PMID 38580884, 2024). "LncRNA LINC02582 could promote breast cancer radioresistance by interacting with deubiquitinating enzyme ubiquitin specific peptidase 7 (USP7) to deubiquitinate and stabilize checkpoint kinase 1 (CHK1), a key molecule in DDR12." (PMID 36323697, 2022). "Based on our results, we confirmed the tumor-promoting function of Usp7 in breast cancer." (PMID 35673573, 2022). "This difference in susceptibility between breast cancer cells and non-cancerous cells was most prominent upon knockdown of Metap2 and Usp7." (PMID 35673573, 2022).
breast carcinoma (continued). "In addition, our data demonstrate a pivotal role of Usp7 for viability and competitive growth of breast cancer cells." (PMID 35673573, 2022). "Importantly, we discovered an advantage for combining Metap1, Metap2 or Usp7 knockdown with PI3K inhibition to target breast cancer cells." (PMID 35673573, 2022). "Taken together, Usp7 knockdown or pharmacological inhibition in human and murine breast cancer cells mediated combinatory and partly synergistic effects to PI3K inhibition that were transferrable to human hepatocellular carcinoma and colorectal cancer cell lines." (PMID 35673573, 2022). "Additionally, Metap1, Metap2 or Usp7 knockdown sensitized PyMG-TA and PyB6-TA breast cancer cells to BKM treatment in comparison to cells with unaltered protease expression." (PMID 35673573, 2022). "Silencing or inhibiting USP7 induces apoptosis and inhibits cell growth in breast cancer." (PMID 34869041, 2021). "USP7 also promotes apoptotic escape of breast cancer cells by deubiquitinating and stabilizing Erα." (PMID 34869041, 2021). "Since inhibition of USP7 induces apoptosis in neuroblastoma, breast cancer and ovarian cancer cells, we hypothesized that inhibition of USP7 could also induce apoptosis in GBM." (PMID 34556124, 2021). "Aberrant overexpression of USP7 has been observed in breast cancer." (PMID 32922122, 2020). "Overall, USP7 as a deubiquitination enzyme might be a molecular regulator in breast cancer and could be a target for future gene-editing strategies." (PMID 32922122, 2020). "Identification of USP7 as a therapeutic target might be possible through detailed gene editing analysis on more invasive breast cancer cell lines and healthy breast epithelial cell lines." (PMID 32922122, 2020). "The authors believe that targeting the USP7-ERα complex could be a potential strategy to treat ERα-positive breast cancer." (PMID 32224970, 2020). "Here, we propose that transcriptionally upregulated ECT2 may enhance USP7 self-deubiquitination thus stabilization in breast cancer." (PMID 32929379, 2020). "USP7 inhibition led to apoptosis of ERα-positive breast cancer cells." (PMID 32224970, 2020). "Hence, the combination of USP7 inhibitors and chemotherapy could reduce drug resistance in individuals with chemotherapy-resistant breast cancer." (PMID 38787520, 2024). "USP7 is overexpressed in many cancer types, such as ovarian cancer, breast cancer (BC), multiple myeloma, hepatocellular carcinoma, glioblastoma, colorectal cancer (CRC), neuroblastoma, squamous cell carcinoma, and lung cancer." (PMID 37658402, 2023). "Interestingly, USP7 also promotes tumorigenesis in breast cancer and cervical cancer." (PMID 35150316, 2022). "Thus, in the current study, we have aimed to identify USP7, which is a deubiquitination enzyme, as a new therapeutic target for breast cancer treatment regardless of TP3 mutation in vitro." (PMID 32922122, 2020). "Targeting ECT2, USP7 or their interaction molecular interface may, thus, abrogate the positive feedback circuit forming by these two molecules, and provide an effective treatment of breast cancer patients." (PMID 32929379, 2020). "FBXW7-mediated ubiquitination targets ZMYND8 for proteasomal degradation, whereas a recent study identified USP7 as a deubiquitinase that stabilizes ZMYND8 and thereby promotes breast cancer cell migration and invasion." (PMID 41297414, 2025).
breast carcinoma (continued). "While USP7 affects the cell cycle of breast cancer, which regulates its growth, USP9X influences breast cancer growth by influencing nuclear replication." (PMID 38613804, 2024). "PROTAC PU7-1, targeting FOXM1 through the involvement of USP7 (Ubiquitin Specific Peptidase 7), significantly reduces FOXM1 protein levels in breast cancer cells and inhibits cell proliferation in MDA-MB-468 (IC50 1.8 μM) and BT549 (IC50 2.8 μM) TNBC cells." (PMID 39594778, 2024). "The EZH2-HMGA1-USP7 complex regulates the formation of CCF, and CCF activates cGAS, but USP7 is required to de-ubiquitinate cGAS and stabilize cGAS, EZH2 can promote breast cancer metastasis through cGAS-STING pathway activated by CCF." (PMID 38312740, 2024). "In terms of treatment, USPs can be used as cancer therapeutic targets, such as inhibitors of USP1, USP4, USP7, USP9X, and USP33 for prostate cancer, lung cancer, breast cancer, and hematological malignancies, among others." (PMID 38613804, 2024). "For instance, both USP7 and PHF8 exhibit high expression in breast cancer and DSB repair relies on PHF8 stabilization, which is enforced by USP7." (PMID 39311138, 2024). "Based on the database of patients with breast cancer (BRCA) from The Cancer Genome Atlas (TCGA), we observed the effect of USP7, MDM2 and DICER mRNA expression levels on the overall survival of patients." (PMID 37867415, 2024). "More convincingly, the interaction of endogenous USP7 and DICER was confirmed in human breast cancer cell lines MDA‐MB‐231 and HCC1937, prostate cancer cell line DU145, and liver cancer cell line HepG2." (PMID 37867415, 2024). "In breast cancer, lncRNA LINC02582 directly interacted with a ubiquitinase USP7, which reduced the level of CHK1 protein, resulting in radioresistance." (PMID 35600868, 2022). "After the micronuclear membrane ruptures, USP7 in CCF can stabilize cGAS to activate the cGAS–STING pathway by reducing the ubiquitination of cGAS, thereby promoting breast cancer metastasis." (PMID 35163710, 2022). "For example, high expression levels of OTUD6B, UCH37, VCPIP1, USP7 and COPS5 were reported in breast cancer." (PMID 34577547, 2021). "In addition, given the essential roles of PHF8 and CHK1 that act as USP7 substrates in DNA damage response, combination of USP7 inhibitors and chemotherapy/radiotherapy may reduce breast cancer cell resistance, which is expected to accelerate the development of breast cancer therapy." (PMID 34869041, 2021). "In summary, the ATM/ZEB1/USP7/CHK1, miR-200c/LINC02582/USP7/CHK1, USP7/PHF8, UCHL3/RAD51, USP52/ASF1A, and UCHL1/HIF-1 signaling axis are potential targets to improve the radiosensitivity of breast cancer." (PMID 34575114, 2021). "Both blockage of deubiquitination by p5091 and knockdown of USP7 reduced cell proliferation, cell migration, colony formation, and sphere dissemination for both MCF7 and T47D breast cancer cell lines." (PMID 32922122, 2020). "To extend our observations to a clinicopathologically-relevant context, we then analyzed the protein expression levels of ECT2, USP7, and MDM2 with breast carcinoma samples and histologically normal mammary tissues." (PMID 32929379, 2020). "Here, siRNA and shRNA strategies and an allosteric small-molecule inhibitor of USP7 were used to define potential anticancer activity against MCF7 and T47D human breast cancer cell lines." (PMID 32922122, 2020). "Due to the complex biological heterogeneity of breast cancer, it will be important to determine to what extent the ECT2/USP7 circuit affects breast cancer cell survival across genetically distinct subgroups of breast cancer." (PMID 32929379, 2020).
breast carcinoma (continued). "For instance, increased expression levels of OTUD6B, UCH37, VCPIP1, USP7, and COPS5 have been detected in various breast cancers." (PMID 33070427, 2020). "Our previous work showed that USP7, a ubiquitin specific protease, was related to TAM sensitivity in Caucasian derived LCLs and inhibition of USP7 resulted in TAM resistance in 2 breast cancer cell lines." (PMID 24699530, 2014). "In addition, several studies showed that NICD protein stability is also regulated by deubiquitinating enzymes such as USP7 and USP8 in T-ALL and breast cancer." (PMID 38043798, 2024). "Our analysis showed that altered USP7 mRNA expression is not restricted to individual subtypes of breast cancer but that expression is evenly distributed between them." (PMID 38672118, 2024). "Mainly USP4, USP7, USP22, UCHL1, UCHL5, and OTUB1 could be used as biomarkers for each type of cancer such as EOC, breast cancer, melanoma, cervical cancer, and colorectal cancer." (PMID 37107644, 2023). "Usp7, Metap1 and Metap2 are synthetic lethal partners of simultaneous protease/PI3K inhibition, which may refine future breast cancer therapy." (PMID 35673573, 2022). "Synergistic effects of combined Usp7 knockdown and PI3K inhibition were analyzed in murine PyB6-TA as well as human MCF7-TA and MDAMB-TA breast cancer cells, using the miR-E-transduced cell lines that generated the most potent protein reduction after 4 and 8 days of Dox treatment." (PMID 35673573, 2022). "Combination of Usp7 knockdown and PI3K inhibition showed an additional cell growth impairment compared to PI3K-inhibitor-only treated cells; an effect that was most prominent in human breast cancer cells and upon use of PI3K-inhibitors at EC10." (PMID 35673573, 2022). "In line with our screen data, Usp7, Metap1, Metap2, and MMP17 could be validated as depletion hits in vitro, whereby targeting reduced MTT viability and competitive breast cancer cell growth." (PMID 36313646, 2022). "Moreover, upregulation of USP7, PHF8, and cyclin A2 has also been found in breast cancers, colon and rectum cancers." (PMID 34869041, 2021). "A previous study demonstrated that USP7 is a DUB of ERα and promoted breast cancer progression." (PMID 34035221, 2021). "Indeed, USP7, PHF8 and cyclin A2 were all found to be upregulated in several breast cancers, as well as in colon and rectum cancers, compared to adjacent tissues." (PMID 32850836, 2020). "Mechanistically, ECT2 together with USP7, forms a positive feedback loop to control the expression of each other, and the reciprocal stabilization of the two molecules fuels oncogenic MDM2 in breast cancer." (PMID 32929379, 2020). "Indeed, USP7 and PLK1 were found to correlate in tissue sections of primary breast cancer and to be highly expressed in taxane-resistant tumors." (PMID 32850836, 2020). "Taken together, these findings demonstrated that miR-200c enhances the radiosensitivity of breast cancer cell by downregulating the miR-200c/LINC02582/USP7/CHK1 signaling axis, thereby playing a critical role in regulating the radiosensitivity of breast cancer cells." (PMID 31601781, 2019). "Thus, exploring the potential of the selective inhibition of USP7 and/or PHF8 enzyme activity, particularly in combination with chemotherapy or radiation therapy, may be worthwhile for treatment refinement of breast cancer." (PMID 39311138, 2024).
breast carcinoma (continued). "Given that USP7 is responsible for stabilizing EZH2 and ERα, it is interesting to consider how USP7 might regulate inflammation by exploiting EZH2 stabilization based on the presence or absence of ER in breast cancer." (PMID 39767641, 2024). "For example, in the most studied breast cancer, CARM1 could methylate the R838 site of lysine demethylase 1 (LSD1) to promote the binding of deubiquitinase USP7, resulting in the ubiquitination and stabilization of LSD1, thereby promoting the invasion and metastasis of breast cancer cells." (PMID 35033016, 2022). "The results showed that ECT2 deletion associated growth retardation of breast cancer cells could be reverted, to certain extent, by forced expression of MDM2 or USP7/wt, but not USP7/C223S." (PMID 32929379, 2020). "Knockdown of Usp7, Metap1 or Metap2 impaired MTT viability to different extent, with both breast cancer cell lines being more sensitive than non-cancerous cells." (PMID 35673573, 2022). "This is likely explained by regulation of PD-L1 by USP7 and USP22 in a tumor type–specific manner, since we have shown previously that CRISPR targeted USP22 deletion resulted in PD-L1 downregulation in human breast cancer cells but not in B16 cells." (PMID 38038129, 2023).